PIK3CA (phosphatidylinositol-4,5-bisphosphate 3-kinase catalytic subunit alpha)
Diseases named in the same sentence as PIK3CA in open-access papers (continued):
Sharing a sentence is not in itself a finding about the gene and the disease.
cancer (continued). "The crystal structure of the complex between p110α and p85α has revealed that a number of the cancer-associated PIK3CA mutations occur at residues lying at the interfaces between p110α and p85α or between the kinase domain of p110α and other domains within the catalytic subunit." (PMID 22949056, 2012). "Of the genes that encode the enzymatic subunit of PI3K heterodimers, the PIK3CA gene that encodes the p110 subunit of PI3K has been found to be most frequently activated by its mutations in some human cancers; this promotes AKT1 phosphorylation to activate a parallel intracellular axis." (PMID 22043994, 2012). "Interestingly, cancer cell lines harboring PIK3CA mutations or PTEN loss appeared to be more sensitive to PX-866." (PMID 24281308, 2012). "Three of these patients had detectable PIK3CA mutations in bone marrow cancer cells." (PMID 22970388, 2012). "PIK3CA amplification was significantly positively associated with cancer-related death (P = 0.01)." (PMID 22292935, 2012). "Sanger sequencing revealed somatic mutations in the known cancer driver genes PIK3CA, and PTEN." (PMID 22912864, 2012). "In addition, human cancer patients harboring PIK3CA mutations are sensitive to targeted therapy using the mTOR inhibitor everolimus, while human cancer patients carrying Kras mutations are resistant to the treatment." (PMID 22666248, 2012). "PIK3CA mutations are frequently diagnosed in diverse cancers and may predict response to PI3K/AKT/mTOR inhibitors." (PMID 23248156, 2012). "This specific dependence on glucose for growth was further illustrated by studies evaluating the effects of targeted disruption of the glycolytic pathway using siRNA and was also found to be present across a wider panel of cancer cell lines harbouring endogenous PIK3CA mutations." (PMID 23028762, 2012). "In addition to gene mutations, copy number alterations of EGFR, KRAS, PIK3CA and other signaling mediators are also critical factors that drive cancer development and determine prognoses and the sensitivity to anticancer drugs." (PMID 22994622, 2012). "PIK3CA amplification was significantly positively associated with cancer-related death." (PMID 22292935, 2012). "Cancers containing PIK3CA mutations are often sensitive to rapamycin and its analogs (rapalogs)." (PMID 22680924, 2012). "The importance of this finding is further emphasized by the fact that pharmacologic MEK pathway inhibition of cell proliferation in BRAF mutant cancers may be significantly decreased by the presence of activating PIK3CA mutations." (PMID 21738740, 2011). "PIK3CA mutations in exons 8, 9 and 20 were observed in 7.0% of cancers." (PMID 21473780, 2011). "Mutated PIK3CA are known to be oncogenic and several inhibitors are in anti-cancer clinical trials." (PMID 21208444, 2011). "This new gene set should help to understand the behavior of PIK3CA-mutated cancers and detailed knowledge of Wnt signaling activation could lead to novel therapeutic strategies." (PMID 21209903, 2010). "For example, PI3Kα inhibitors might be tested against xenografts of human cancer cell lines which have mutations of PIK3CA, for obvious reasons." (PMID 21179398, 2010). "These dual inhibitors may effectively shutdown PI3K/AKT signalling in cancers with PIK3CA and/or PIK3R1 mutations, PTEN loss, and RTK-dependent activation, all features that embody a large number of GBMs." (PMID 20515495, 2010). "The tumors carrying exon 9 PIK3CA mutations are more likely to be low-grade carcinomas; in contrast, carcinomas with exon 20 mutations or PIK3CA mRNA overexpression are often high-grade carcinomas associated with myometrial invasion and tended to have lymphovascular invasion." (PMID 20368795, 2010). "Based on these results, we hypothesized that PIK3CA activating mutations may be associated with lesser chemotherapy sensitivity and more residual cancer after preoperative chemotherapy." (PMID 18371219, 2008).
cancer (continued). "In vitro evidence suggests that PIK3CA (phosphatidylinositol 3-kinase, catalytic, alpha polypeptide) activation may be associated with altered chemotherapy sensitivity in cancer." (PMID 18371219, 2008). "Given the high degree of PIK3CA mutations in human cancers, this could have a tremendous impact on eliminating the morbidity and mortality of malignant diseases." (PMID 16449998, 2006). "More recently, PIK3CA mutations were identified in different human cancers." (PMID 16168105, 2005). "Combining the PtenR173C mutation in mouse models carrying additional cancer drivers (such as PIK3CA mutation) or defects in DNA repair genes (such as Brca or Rad51) could provide evidence for this speculation, but such experiments are outside the scope of the current study." (PMID 41215730, 2026). "Additionally, patients aged 65 and older with squamous CC show a higher frequency of PIK3CA mutations, which are associated with increased mutation rates in other genes involved in key cancer-associated pathways, such as tyrosine kinase receptors, K-Ras/BRAF/MAPK and the Wnt/β-catenin pathway." (PMID 40003544, 2025). "The possibility that PIK3CA might represent an outlier in terms of its patterns of mutation expression is supported by orthogonal analysis, in which PIK3CA mutations across six cancer types exhibit low RNA VAF despite being predicted by BoostDM to be driver mutations." (PMID 40514689, 2025). "Notably, PIK3CA mutations were associated with numerous cancers." (PMID 39678496, 2024). "Similarly, PIK3CA mutations have been commonly identified in colon, brain, and other organ cancers." (PMID 39685930, 2024). "PIK3CA variations, in conjunction with other genetic mutations, can influence cancer progression and, therefore, may play a crucial role in determining targeted therapeutic approaches to cancer." (PMID 39685930, 2024). "Finally, we found a decreased ERBB2 expression in carcinomas with an activating PIK3CA mutation." (PMID 38893129, 2024). "Additionally, around 30% of these cancers harbour PIK3CA mutations, suggesting that adjuvant PIK3CA inhibitors may represent a class of drugs worth investigating in prospective clinical trials." (PMID 37935787, 2023). "Intervention in glutamine metabolism could facilitate treatment for cancers with mutated PIK3CA." (PMID 36959802, 2023). "In addition, PIK3CA mutations have also been linked to cancer initiation through ER signaling." (PMID 37454130, 2023). "To establish whether the PIK3CA public NeoAg is spontaneously immunogenic, we collected PBMC samples from n = 14 HLA-A*03:01+ patients with a history of a Mut PIK3CA cancer identified using MSK-Integrated Mutation Profiling of Actionable Cancer Targets (IMPACT) 43–45." (PMID 35484264, 2022). "Investigations using a larger number and more diverse types of human cancers should be conducted to elucidate the pathological relevance of the fluctuations in each acyl variant as well as their interaction with changes in oncogenes and tumor suppressor genes such as PIK3CA, K-, H-RAS, and PTEN." (PMID 35013169, 2022). "Thus, concomitant PIK3CA mutations could provide the required WNT/β-catenin pathway activation in BRAF mutated cancers." (PMID 36079062, 2022). "In the following, we will discuss several signal transduction pathways whose deregulation may be mechanistically related to the effects of PIK3CA mutations in cancer development and progression, as well as to particularities of aspirin action in affected individuals." (PMID 35780223, 2022). "For some cancer types, a PIK3CA mutation may just be a subclonal driver mutation." (PMID 33723724, 2021).
cancer (continued). "In addition, a comparative analysis of the MBCs subjected to WES or targeted cancer gene sequencing (n = 44) revealed that MBCs harboring TERT promoter hotspot mutations or gene amplification (n = 6) more frequently harbored PIK3CA than TERT wild-type MBCs (n = 38; p = 0.001; Fisher’s exact test)." (PMID 33863915, 2021). "Whereas the growth of PIK3CA-mutated cancer including CRC is dependent on glucose metabolism, recent reports demonstrated that PIK3CA mutations in CRC confer the dependency on glutamine metabolism, which may be targetable to suppress the growth of PIK3CA-mutated CRC." (PMID 32365457, 2020). "The CN state of chromosomes 1, 11 or 16 as well as the PIK3CA mutation status of IDPs diagnosed in biopsies could be evaluated further as an assay to predict which subset of patients diagnosed with IDP could have the potential to develop carcinoma." (PMID 32195332, 2020). "Many human cancers feature oncogenic alterations in PIK3CA, and not only do these often occur with mutations in other pathway components, but our data demonstrate the frequent presence of more than one mutant PIK3CA copy, suggesting that cancer cells benefit from additional PI3K pathway activation." (PMID 30948643, 2019). "Notably, inhibitors of the PIK3-Akt-mTOR pathway have been developed as cancer target therapy alternatives, and patients harboring PIK3CA gene mutations could be potential candidates for such therapeutic approach." (PMID 30619505, 2018). "Consequently, addressing PIK3CA mutation status in cancer patients may provide a more accurate molecular diagnosis enabling tailored therapeutic approaches." (PMID 29523855, 2018). "It is possible that a PIK3CA mutation may act differently at cancer initiation than at progression." (PMID 27283966, 2016). "Thus, PIK3CA mutation has been involved in molecular pathway of cancer." (PMID 27388016, 2016). "However, the fact that PIK3CA mutations can reprogram cancer metabolism, as demonstrated herein, was previously unknown." (PMID 27321283, 2016). "Thus, PIK3CA-mutated patients had significantly more often a cancer history (p<0.001, Chi square)." (PMID 25473901, 2015). "Exome sequencing revealed a number of altered genes implicated in cancer that are specific to the MCF10CA1a line and which may represent alterations which, in addition to the mutation in PIK3CA, are required to impart tumourigenic properties upon the MCF10A line." (PMID 25969993, 2015). "The trees reveal insights into three aspects of cancer evolution that are of future clinical relevance: phylogenetic relationships among the pre-invasive lesions and with the IDCs, lineage heterogeneity of pre-invasive lesions, and recurrence of mutations in PIK3CA." (PMID 25918554, 2015). "However according to our study, the dysregulation of PI3K pathway caused by PIK3CA mutation could possibly cooperate with the altered signal pathway(s) to make the patients with family cancer history to have worse survival." (PMID 25054828, 2014). "Moreover, even so-called dual-targeting of HER2 may not be sufficient to overcome resistance to HER2 inhibition, particularly in the case of HER2-amplified cancer with a PIK3CA mutation." (PMID 24451154, 2014). "This suggests that while PIK3CA activating mutations may be important for generating early neoplasia, they may not be a prominent player in promoting the progression to cancer at this early stage, despite known PIK3CA-associated expression differences at the carcinoma stage." (PMID 24887547, 2014). "However, it remains unclear whether PIK3CA-activating mutations might preclude the anti-cancer activity of metformin in vivo." (PMID 23986086, 2013). "Thus, metformin can no longer be considered as a bona fide DR mimetic, at least in terms of anti-cancer activity, because tumors harboring the insulin-unresponsive, DR-resistant, PIK3CA-activating mutation H1047R remain sensitive to the anti-tumoral effects of the drug." (PMID 23986086, 2013).
cancer (continued). "Given the high prevalence of PIK3CA mutations in human carcinomas and the emerging role of PIK3CA mutation status in the treatment selection process, these findings might have a significant impact on the design of future trials evaluating the potential of combining metformin with targeted therapy." (PMID 23986086, 2013). "PIK3CA mutations may act as driver mutations in certain cancers responsible for metastasis." (PMID 23455493, 2012). "The BBO-10203 drug blocks the interaction between RAS and the PI3Kα RBD, inhibiting PI3Kα signaling in both wild-type and PIK3CA-mutant cancer cell lines." (PMID 41272322, 2026). "Two patients harbored additional pathogenic germline variants in cancer predisposition genes: 1 in RAD51C and 1 in PIK3CA." (PMID 41487701, 2026). "The PIK3CA gene encodes p110α, the catalytic subunit of Class IA PI3K, and its mutations have been reported in various cancer types." (PMID 40638603, 2025). "The study met its primary endpoint of an overall response rate (ORR) of 16%, showing that copanlisib was a promising inhibitor for patients with PIK3CA-mutant cancers." (PMID 40564038, 2025). "In the context of EC, MuTect2 has been instrumental in uncovering mutations in key genes such as PTEN, PIK3CA, and ARID1A, which are frequently altered in this cancer type." (PMID 39858102, 2025). "Cancer-associated genetic alterations in MYC, PIK3CA, PTEN, KRAS, and BRAF dysregulate growth-promoting signals, enhancing ribosome production and protein synthesis." (PMID 40805230, 2025). "Phosphatidylinositol-4,5-bisphosphate 3-kinase catalytic subunit alpha (PIK3CA) mutations, associated with KRAS foster cell growth in various cancers, including CRC." (PMID 40943367, 2025). "Specific mutated genes began to be identified in the blood of cancer patients in the form of ctDNA about 20 years ago, including KRAS and PIK3CA in patients with colorectal cancer, EGFR in breast cancer patients and in NSCLC patients." (PMID 41294857, 2025). "Low PIK3R1 expression was more frequent in cancers with PIK3CA amplifications than those with PIK3CA WT tumors (64%, 14/22 vs. 38%, 24/64, p = 0.033)." (PMID 39858051, 2025). "To understand this observation further, we analyzed data from The Cancer Genome Atlas (TCGA) Pan-Cancer Atlas, which verified a significant co-occurrence of KRAS and PIK3CA mutations in CRC." (PMID 39808497, 2025). "PIK3CA mutations were also common, with an overall incidence of 11.5% (10/87) and incidences of 13.1% (8/61) and 7.7% (2/26) in HER2-amplified cancers of the colon and rectum, respectively." (PMID 40742050, 2025). "PDEECs with MMR deficiency exhibit increased genomic instability, leading to the accumulation of mutations across various cancer-related genes, including PTEN, PIK3CA, and ARID1A." (PMID 40072110, 2025). "Aberrant activation of this pathway, commonly resulting from mutations in PIK3CA, loss of PTEN tumor suppressor function, or receptor tyrosine kinase overexpression, confers growth advantages and therapeutic resistance to cancer cells." (PMID 41226270, 2025). "In contrast, seven out of ten anti-AD core targets (PTGS2, MAPK1, MAPK3, JUN, ESR1, IL6, and PIK3CA) followed the pathways in cancer." (PMID 40179089, 2025).
cancer (continued). "While much attention has been given to the fact that PIK3CA (encoding PI3Kα) is a frequently mutated gene in cancer, it is striking that mutations in the broader PI3K/AKT/mTOR pathway significantly outweigh PIK3CA mutations in solid tumours." (PMID 40360883, 2025). "This initial discovery was expanded to include multiple cancer types, such as GBMs, gastric, breast, and lung cancers, leading to the recognition of PIK3CA as a key oncogene." (PMID 40508087, 2025). "Mutation frequencies vary across different cancers, but in CRC, PIK3CA alterations are particularly notable due to their involvement in metabolic reprogramming and chemoresistance." (PMID 40949797, 2025). "The “High Signal” list affected 24 cancer drivers, encompassing key genes such as PIK3CA, MTOR, RAF1, and JUN." (PMID 39975128, 2025). "This allowed us to accurately determine the MAFs of somatic mutations and identify clonal proliferation of adenomyotic epithelium with cancer-associated gene mutations as represented by KRAS and PIK3CA mutations using TS." (PMID 40679511, 2025). "These mutations have been observed across various cancer types, but they seem to present a distinct pattern in EC, strengthening the hypothesis that ECs exhibit a unique spectrum of somatic mutations in the PIK3CA gene, particularly in the amino-terminal domain of p110-α." (PMID 40507285, 2025). "Unlike pan‐PI3K inhibitors, taselisib is believed to have fewer side effects and greater efficacy in treating PIK3CA‐mutant cancers, owing to its selective action on these specific PI3K isoforms." (PMID 41049266, 2025). "The anti-cancer properties of LBP in GC cells are associated with the increased expression of miR-202, which disrupts the PIK3CA/AKT/mTOR pathway." (PMID 39897859, 2025). "Pathogenic variants in the PIK3CA gene, which encodes the p110-α catalytic subunit of the phosphoinositide 3-kinase (PI3K), are commonly associated with overgrowth syndromes and cancer." (PMID 41357804, 2025). "Mutations in pathway-related genes, such as KRAS, NRAS, BRAF, and PIK3CA, influence treatment responses and serve as key prognostic indicators in cancer treatment." (PMID 40279317, 2025). "p85 subunit helical domain mutations (E542K, E545K) prevent binding to PIK3CA, leading to unrestrained PI3K activity and elevated AKT signaling leading to enhanced cancer cell proliferation and viability." (PMID 40072110, 2025). "The role of the circRNA/hsa-miR-11181-5p/PIK3CA axis in cancer, particularly RB, remains unreported." (PMID 40535798, 2025). "The dysregulation of this cellular pathway, often driven by mutations in KRAS or PIK3CA common in MSS tumors like SW480, is frequently observed in various cancers including CRC, making it an attractive target for cancer therapy." (PMID 40918508, 2025). "GCT-007 (Global Cancer Technology) is a brain-penetrant, highly selective inhibitor of p110α the catalytic subunit of PI3Kα (PIK3CA), making it a promising candidate for HGGs." (PMID 40386392, 2025). "Associations with PTEN loss, PIK3CA mutation, and RICTOR amplification were estimated using linear models adjusted for cancer type." (PMID 41300706, 2025).